BTN3A1 (butyrophilin subfamily 3 member A1)
Description:
Plays a role in T-cell activation and in the adaptive immune response. Regulates the proliferation of activated T-cells. Regulates the release of cytokines and IFNG by activated T-cells. Mediates the response of T-cells toward infected and transformed cells that are characterized by high levels of phosphorylated metabolites, such as isopentenyl pyrophosphate.
Synonyms: CD277; BTF5; BT3.1; BTN3.1
Tractability: Small molecule: a structure with a bound ligand is known; a high-quality ligand is known. Antibody: UniProt places it where antibodies can reach, with high confidence; its Gene Ontology location is reachable by antibodies, with high confidence; UniProt predicts a signal peptide or a membrane-spanning region. PROTAC: ubiquitination databases record sites on it; its protein half-life has been measured; a small molecule that binds it is known.
Gene: Protein-coding gene on chromosome 6 (26,402,237 to 26,415,216, forward strand). Ensembl gene ENSG00000026950.
Subcellular location: Cell membrane
Subcellular location (Human Protein Atlas): Vesicles
Pathways (Reactome):
Immune System: Butyrophilin (BTN) family interactions
Gene Ontology:
Molecular function: protein binding; signaling receptor binding
Biological process: activated T cell proliferation; positive regulation of cytokine production; positive regulation of type II interferon production; T cell receptor signaling pathway; regulation of cytokine production
Cellular component: plasma membrane; external side of plasma membrane
Genetic constraint (gnomAD): Loss-of-function variants: 23 observed, 39.06 expected, observed/expected ratio (o/e) 0.59, 90% interval 0.42 to 0.83. The synonymous counts are far from expectation, so gnomAD's model fits this gene poorly and the ratio says little. Missense variants: 512 observed, 599.49 expected, observed/expected ratio (o/e) 0.85, 90% interval 0.79 to 0.92. Synonymous variants: 174 observed, 223.91 expected, observed/expected ratio (o/e) 0.78, 90% interval 0.69 to 0.88.
Homologues: Orthologues: chimpanzee BTN3A1 (95% identical), macaque BTN2A2 (77% identical), mouse Btnl12 (10% identical), rat Btnl12 (9% identical). Paralogues in human: BTN3A3 (85% identical), BTN3A2 (52% identical), BTN1A1 (47% identical), BTN2A2 (44% identical), BTN2A1 (42% identical), BTNL9 (39% identical), BTNL3 (31% identical), BTNL8 (30% identical), ERMAP (29% identical), BTNL2 (24% identical), MOG (15% identical), CD276 (14% identical), and 3 more.
Diseases named in the same sentence as BTN3A1 in open-access papers:
BTN3A1 is named in the same sentence as 64 diseases in open-access papers, as found by Europe PMC text mining. Sharing a sentence is not in itself a finding about the gene and the disease. The quoted sentences say what the papers report.
ovarian carcinoma (9 papers, 2015 to 2025). A malignant neoplasm originating from the surface ovarian epithelium. "In datasets derived from the Affymetrix gene chips, higher expression of BTN3A1 was associated with better prognosis in breast cancer, ovarian cancer, gastric cancer, and NSCLC." (PMID 34293829, 2021). "Through the analysis of 65 high-grade serous ovarian cancers, our study showed significant enrichment of both the expression of BTN3A1 and the accumulation of γδ T cells in human ovarian cancer compared to tumor-free ovaries or the fallopian tube." (PMID 38541651, 2024). "Because ovarian cancer is stubbornly resistant to conventional PD-1 blockers, this study provided a good rationale for testing BTN3A1-modifying, Vγ9Vδ2 T cell-activating antibodies." (PMID 38541651, 2024). "Together, αβ and γδ T cells elicited superior control of established ovarian cancer xenografts in response to these BTN3A1 antibodies, in a manner that was superior to PD-1 checkpoint therapy and dependent on the expression of a second butyrophilin (BTN2A1)." (PMID 38541651, 2024). "A recent study reported that BTN3A1-targeted therapy showed superior efficacy to PD-1 checkpoint therapy in validated orthotopic xenograft and syngeneic models of ovarian cancer." (PMID 36033440, 2022). "As a matter of fact, BTN3A1 expressed on APCs has been shown to restrain human T cell proliferation in ovarian carcinoma microenvironments." (PMID 36362212, 2022). "In addition, BTN3A1 is dysregulated in different types of human cancer, including breast cancer, ovarian cancer, bladder cancer, renal cell carcinoma, and pancreatic ductal adenocarcinoma." (PMID 36418890, 2022). "Then, BTN3A1 could dynamically coordinate αβ and γδ T-cell-driven antitumor immunity to eliminate the malignant progression of ovarian cancer." (PMID 36211333, 2022). "In addition, BTN3A1 is expressed in many tumors, such as ovarian cancer, bladder cancer, breast cancer, renal cell carcinoma and pancreatic ductal adenocarcinoma." (PMID 36418890, 2022). "Targeting BTN3A1 in vivo using CTX-2026, a unique fully human aglycosylated monoclonal antibody delayed the progression of ovarian cancer in both syngenic and xenograft models through the elicitation of more robust αβ T cell responses." (PMID 37240071, 2023). "Human BTN3A1, also known as CD277, is highly upregulated in myeloid DCs and macrophages by vascular endothelial growth factor (VEGF) and CCL3 in human ovarian cancer." (PMID 26347744, 2015). "Targeting BTN3A1 with novel human antibodies that promote the formation of a complex of this butyrophilin with BTN2A1 elicited coordinated αβ and Vγ9Vδ2 T cell responses against established ovarian cancer xenografts, including orthotopic tumors." (PMID 38541651, 2024).
breast carcinoma (7 papers, 2020 to 2023). "BTN3A1 was altered in most cancers and was downregulated and positively associated with prognosis of patients with non‐small cell lung cancer and breast cancer." (PMID 34293829, 2021). "BTN3A1 expression was downregulated in breast cancer and NSCLC, and was positively associated with clinical outcome of the patients." (PMID 34293829, 2021). "BTN3A1 was associated with tumor‐infiltrating immune cells and was co‐expressed with multiple immune checkpoints in patients with breast cancer (BRCA) and non‐small cell lung cancer (NSCLC)." (PMID 34293829, 2021). "Zhang’s Lab) and found that higher BTN3A1 expression was associated with longer overall survival in cutaneous melanoma, and increased expression of BTN3A1 was also positively associated with the infiltration of γδ T cells into tumor tissues (lung and breast cancer)." (PMID 37629075, 2023). "BTN3A1 is related to the prognosis of ovarian cancer, breast cancer, bladder cancer, pancreatic ductal adenocarcinoma and renal cell carcinoma." (PMID 34149914, 2021). "BTN3A1 was highly expressed in advanced ovarian cancer 2, but down-regulated in breast cancer." (PMID 34149914, 2021). "The results suggested that BTN3A1 may have a role in shaping the immunosuppressive tumor microenvironment and may sever as a tumor suppressor in breast cancer and NSCLC by promoting the invasion of innate and adaptive immune cells and inhibition of the invasion of MDSCs." (PMID 34293829, 2021). "Among them, there are many studies on tumor immunity of BTN3A1, which shows that it is essential for the activation of Vγ9Vδ2 T cells, while BTN3A3 is expected to become a potential therapeutic target for breast cancer." (PMID 34149914, 2021).
COVID-19 (3 papers, 2022 to 2025). A disease caused by infection with severe acute respiratory syndrome coronavirus 2. "BTN3A1, an immune system protein involved in T-cell activation and regulation, is part of a 5-gene signature that predicts ventilator-free days in patients with COVID-19." (PMID 41325417, 2025). "Among these 16 protein-coding genes, the roles of BTN3A1, EIF5A, and NDUFA6 were previously identified in the pathogenesis of COVID-19, suggesting a potential link between their expression and the development of Long COVID." (PMID 41325417, 2025). "This phenomenon reflects the discussions in the Introduction that RIPK3 is related to the natural essence of COVID-19, while ATP6V1B2, IFI27, BTN3A1, SERTAD4, and EPSTI1 contain more information about SARS-CoV-2." (PMID 36298522, 2022).
glioma (3 papers, 2022 to 2024). A benign or malignant brain and spinal cord tumor that arises from glial cells (astrocytes, oligodendrocytes, ependymal cells). "Although Vγ9Vδ2 T cells derived from human PBMCs demonstrated good cytotoxicity against gliomas that overexpress BTN2A1/BTN3A1, such overexpression occurred in less than 30% of GBM cases." (PMID 37770968, 2023). "Recognizing the clinical limitations of ZOL and BTN3A1 agonistic antibody in glioma, especially given the high B7H3 expression in the majority of GBM cases, we genetically engineered Vγ9Vδ2 T cells into Car-B7H3-γδT cells." (PMID 37770968, 2023). "This led us to explore the use of zoledronate, a bisphosphonate drug that inhibits farnesyl diphosphate synthase to accumulate DMAPP and IPP, or a BTN3A1 agonistic antibody 20.1 to sensitize WAT primary glioma cells to Vγ9Vδ2 T cell killing." (PMID 37770968, 2023). "Protein expression of BTN2A1 and BTN3A1, along with gene expression related to lipid metabolism and glioma inflammatory response pathways, is analyzed in matched tumor tissue samples." (PMID 37770968, 2023). "Our results showed that the killing of Vγ9Vδ2 T cells against primary glioma cells was significantly enhanced after ZOL or BTN3A1 agonistic antibody stimulation." (PMID 37770968, 2023). "The SAT group exhibits elevated protein expression of BTN2A1 and BTN3A1, accompanied by differential gene expression related to lipid metabolism and glioma inflammatory response pathways." (PMID 37770968, 2023). "In conclusion, the high expression of BTN2A1/BTN3A1 may serve as a potential indicator for pre-screening Vγ9Vδ2 T cells derived from healthy human PBMCs for glioma treatment." (PMID 37770968, 2023). "Consequently, targeting BTN3A1 could offer novel therapeutic avenues for the management of advanced gliomas." (PMID 38863709, 2024). "High BTN2/3 expression was correlated with OS among sexes (except BTN3A3 in women), WHO grade II (BTN2A2), III (BTN2A2, BTN3A1, and BTN3A2), and IDH-Mut (BTN2A2 and BTN3A2) in glioma." (PMID 36033440, 2022).
schizophrenia (3 papers, 2022 to 2026). A major psychotic disorder characterized by abnormalities in the perception or expression of reality. "However, we conducted a cross-analysis of potential sites associated with depression and schizophrenia, which revealed four intersecting sites: BTN3A1, CYP21A2, PSMB4, and TIMP4." (PMID 38637810, 2024). "We have identified shared comorbidity loci between schizophrenia and depression, including BTN3A1, PSMB4, and TIMP4." (PMID 38637810, 2024). "Shared comorbidity loci between depression and schizophrenia included BTN3A1, PSMB4, and TIMP4." (PMID 38637810, 2024).
acute myeloid leukemia (2 papers, 2018). Acute myeloid leukemia (AML) is a group of neoplasms arising from precursor cells committed to the myeloid cell-line differentiation. "On THP-1 cells [human monocytic cell line derived from acute myeloid leukemia (AML) patient], depletion of BTN3A1 inhibited the cytoplasmic nucleic acid- or virus-triggered activation of IFN-β production, suggesting that BTN3A1 may be a novel regulator of type I IFN responses." (PMID 30050536, 2018).
autoimmune disease (2 papers, 2023 to 2025). A disorder resulting from loss of function or tissue destruction of an organ or multiple organs, arising from humoral or cellular immune responses of the individual to their own tissue constituents. "Currently, there are limited studies on BTN3A1 and autoimmune diseases." (PMID 40959207, 2025). "Selectively blocking BTN3A1’s binding to BTN2A1 may enable selective inhibition of aberrant Vγ9Vδ2 T cell activation in autoimmune diseases." (PMID 37674084, 2023). "However, it remains to be elucidated whether BTN3A1 is involved in the pathogenesis of autoimmune diseases such as SLE by regulating IL‐38." (PMID 40959207, 2025).
cervical cancer (2 papers, 2022 to 2025). A primary or metastatic malignant neoplasm involving the cervix. "This study provides proof‐of‐concept evidence showing that through direct killing, antigen presentation, and competitively binding to BTN3A1, Vγ9Vδ2 T cells amplified from cervical cancer (CC) patients can synergize with αβ T cells to exert anti‐CC function both in vitro and in vivo." (PMID 40091603, 2025). "In other words, BTN3A1 had inhibitory effects on the development of cervical cancer." (PMID 36185274, 2022). "In cervical cancer, BTN3A1 overexpression could inhibit the cervical cancer cell phenotype." (PMID 36185274, 2022).
colorectal cancer (2 papers, 2020 to 2024). A primary or metastatic malignant neoplasm that affects the colon or rectum. "Interestingly, it has been shown in colorectal cancer that Zol can induce the expression of BTN3A1 within the tumor microenvironment thus stimulating effector γδ T cells with antitumor activity." (PMID 32435249, 2020).
cutaneous melanoma (2 papers, 2021 to 2023). A primary melanoma arising from atypical melanocytes in the skin. "In GEPIA datasets, higher BTN3A1 expression was associated with longer overall survival in patients with BLCA, mesothelioma (MESO), KIRC, and skin cutaneous melanoma (SKCM), whereas higher BTN3A1 expression was associated with worse prognosis in patients with brain lower grade glioma (LGG)." (PMID 34293829, 2021).
gastric cancer (2 papers, 2021 to 2024). A primary or metastatic malignant neoplasm involving the stomach. "To investigate this possibility, we first overexpressed BRRF1 in EBV-infected cell lines (HK1-EBV and HONE1-EBV), clinically derived NPC cell lines (C666-1 and NPC43), and gastric cancer cell lines (AGS, NCC-24 and SNU719), and detected the gene expression of BTN2A1 and BTN3A1, via RT–qPCR." (PMID 39769218, 2024).
melanoma (2 papers, 2021 to 2025). A malignant, usually aggressive tumor composed of atypical, neoplastic melanocytes. "The cBioportal was used to investigate the mutations of this gene, and the results showed that BTN3A1 was mutated in cancers of uterine, CHOL, melanoma, and others." (PMID 34293829, 2021). "Additionally, stress-induced molecules such as Butyrophilin Subfamily 3 Member A1 (BTN3A1) and MHC class I-related chain B (MICB) are induced, resulting in melanoma metastasis regression." (PMID 40005571, 2025).
mesothelioma (2 papers, 2021 to 2023). A usually malignant and aggressive neoplasm of the mesothelium which is often associated with exposure to asbestos. "Flow cytometry was used to examine expression of BTN2A1, BTN3A1, PD-L1, PD-L2 on mesothelioma cell lines." (PMID 38077396, 2023). "Therefore, our analysis reveals that the expression of BTN2A1/BTN3A1 is low on the tumor cells in mesothelioma, where a high percentage of cells express PD-L1/PD-L2, which could hinder the effectiveness of Vδ2 T cells for immunotherapy." (PMID 38077396, 2023). "As the results suggest that Vδ2 T cells have certain effectiveness against mesothelioma, we next examined the expression of BTN2A1, BTN3A1, and PD-L1 in mesothelioma tumor tissue sections obtained from the mice experiments described earlier, at the time of death between 17-21 days." (PMID 38077396, 2023).
parasite infection (2 papers, 2025). "Intracellular cytokine staining confirmed that Vγ9Vδ2 T cells produced most of this cytokine: parasite infection increased both the frequency of TNFα-positive Vγ9Vδ2 T cells and their iMFI, whereas BTN3A1 inhibition returned both measures to baseline." (PMID 40667022, 2025). "Together, these results support a model in which Vγ9Vδ2 T cells are activated through BTN3A1, while IL-12 and TNFα license NK cells to produce IFNγ during parasite infection." (PMID 41452934, 2025).
serous ovarian cancer (2 papers, 2022 to 2024). "Thus, our group reported for the first time the association between the density of infiltration of γδ T cells in treatment-naïve high-grade serous ovarian cancer and overall survival, in addition to responsiveness to BTN3A1-targeted antibodies." (PMID 38541651, 2024).
Arthritis (1 paper, 2025). Inflammation of a joint. "Subgroup analysis showed that plasma levels of BTN3A1 were significantly related to several clinical and laboratory features, such as vasculitis, arthritis, cylindruria, and were significantly correlated with C3, RF expression." (PMID 40959207, 2025).
asthma (1 paper, 2026). "We also noted family members of butyrophilin (BTN) proteins–immunomodulatory transmembrane proteins involved in recognition of microbial antigens–prioritised in both CD and asthma (BTN3A1 and BTN3A2), specific to ILC3 cells." (PMID 41573945, 2026).
bladder tumor (1 paper, 2022). "Since BTN3A1 is a critical activating ligand for Vδ2 T cells, this result suggests that Vδ2 T-cell subsets might be involved in bladder tumor control." (PMID 36002184, 2022).
bladder urothelial carcinoma (1 paper, 2021). "In datasets based on RNA‐seq, higher expression of BTN3A1 was associated with better prognosis in bladder urothelial carcinoma (BLCA), rectum adenocarcinoma (READ), sarcoma (SARC), and UCEC." (PMID 34293829, 2021).
breast adenocarcinoma (1 paper, 2015). "A lower molecular mass band of 37 kDa was evident using the BTN3A1-specific Ab 056, particularly in human breast adenocarcinoma MCF-7 cells, indicative of alternative splicing or proteolytic cleavage of BTN3A1." (PMID 25637025, 2015).
ischemic stroke (1 paper, 2025). A stroke disorder caused by obstruction of blood flow to the brain, due to thrombotic (local blood clot formation) or embolic (due to a blood clot or other material traveling from another site) event. "In another study, BTN3A1 was also found differentially expressed in patients with ischemic stroke (significant overlap) and ICH versus controls." (PMID 41353157, 2025).